FMR1 (fragile X messenger ribonucleoprotein 1)
Diseases named in the same sentence as FMR1 in open-access papers (continued):
Sharing a sentence is not in itself a finding about the gene and the disease.
fragile X syndrome (continued). "Fragile X syndrome (FXS) is an X-linked neurodevelopmental disorder caused by a CGG•CCG repeat expansion in the 5′-UTR of the FMR1 gene." (PMID 31098852, 2019). "The CYFIP1 gene is known to interact with the WAVE regulatory complex and proteins from two genes: RAC1, disruption of which causes an autosomal dominant form of intellectual disability, and FMR1, the causative gene for fragile X syndrome." (PMID 30909440, 2019). "Reduced expression of FMR1 causes fragile X syndrome, the most common cause of familial intellectual disability." (PMID 30909440, 2019). "For control purposes we used a multiplexing approach by cotargeting, enriching, and isolating a fragile X syndrome–associated CGG triplet repeat located within FMR1, at the same time as the FECD-associated CTG18.1 locus." (PMID 30733599, 2019). "Increased G4 structure stability upon methylation of d(CGG)n oligomers was therefore implicated in repression of FMR1 in fragile X syndrome." (PMID 30736345, 2019). "Fragile X syndrome (FXS) is caused by silencing of the FMR1 gene leading to loss of the protein product fragile X mental retardation protein (FMRP)." (PMID 30654445, 2019). "Fragile X syndrome (FXS) is a genetic syndrome with intellectual disability due to the loss of expression of the FMR1 gene located on chromosome X (Xq27.3) and characterized by an extension of the cytosine-guanine-guanine sequence (CGG) (> 200 copies)." (PMID 31885726, 2019). "Mutations of the fragile X mental retardation 1 (FMR1) gene involving > 200 cytosine-guanine-guanine (CGG) repeat expansions in the 5′-untranslated region cause fragile X syndrome is the leading inherited cause of intellectual disability." (PMID 30665341, 2019). "Mutations of FMR1 lead to fragile X syndrome and now recognized as the leading cause of familial intellectual disability." (PMID 31207912, 2019). "The transcriptional silencing of the FMRP gene FMR1 causes fragile X syndrome (FXS), which is characterized by a range of physical, behavioral and cognitive deficits and is the leading monogenic cause of autism and intellectual disability." (PMID 31209152, 2019). "Fragile X syndrome (FXS) is a neurodevelopmental disorder caused by silencing of the FMR1 gene and subsequent loss of its protein product, fragile X retardation protein (FMRP)." (PMID 31200759, 2019). "The expansion of the trinucleotide CGG repeats in Fmr1 5′UTR results in FMRP deficiency and finally causes the Fragile X syndrome, which is a common disease belonging to the ASDs." (PMID 30911036, 2019). "Fragile X syndrome (FXS) is a genetic syndrome with intellectual disability due to the loss of expression of the FMR1 gene located on chromosome X (Xq27.3)." (PMID 31885726, 2019). "Inactivation of BK channel by transcriptional silencing of the Fmr1 gene causes the most common inheritable ID, known as Fragile X syndrome (FXS)." (PMID 29370161, 2018). "We describe a female infant with Fragile-X syndrome, with a fully expanded FMR1 allele and preferential inactivation of the homologous X-chromosome carrying a de novo deletion." (PMID 29747568, 2018). "Historically, investigations of the FMR1 phenotype have focused almost exclusively on two clinical conditions associated with CGG expansion: fragile X syndrome and FMR1 premutation associated disorders." (PMID 30197656, 2018). "Fragile X syndrome is predominately caused by an expansion of a trinucleotide (CGG)n repeat present in the 5′ untranslated region of exon 1 of the FMR1 gene." (PMID 33072935, 2018). "The CGG repeat in the 5′ untranslated region of the FMR1 gene is responsible for three major clinical phenotypes: fragile X syndrome (FXS), fragile X-associated tremor/ataxia syndrome (FXTAS), and fragile X-associated primary ovarian insufficiency (FXPOI)." (PMID 30123240, 2018). "Deficiency in FMR1 gives rise to Fragile X Syndrome, a genetic disease with a multitude of symptoms including intellectual deficiency and speech and language impairment." (PMID 29360038, 2018).
fragile X syndrome (continued). "Behavior is often used as proxy to study memory and cognitive deficits in animals like Fmr1-KO mice that model Fragile X Syndrome, the most prevalent single-gene cause of intellectual disability and autism." (PMID 29346381, 2018). "Fragile X syndrome (FXS) is caused by the maternal expansion of an unstable CGG-repeat tract located in the first exon of the FMR1 gene." (PMID 30147707, 2018). "Mutations of the FMR1 gene play a role in the development of three different conditions; the fragile X syndrome, premature ovarian failure and the tremor/ataxia syndrome (FXTAS)." (PMID 29986653, 2018). "Fragile X syndrome is caused by the reduced expression of FMRP, a protein translation repressor protein encoded by the Fmr1 gene." (PMID 30042656, 2018). "ASD-like phenotypes induced by the Fmr1 mutation, a gene responsible for Fragile X syndrome, are able to be alleviated by administration of mGluR antagonists in mouse models." (PMID 30524240, 2018). "Several studies investigated the epigenetic modificationsof the FMR1 gene in the full mutation alleles associatedwith fragile X syndrome." (PMID 29308622, 2018). "Fragile X syndrome (FXS) is an inheritable neuropsychological disease caused by silence of the fmr1 gene and the deficiency of Fragile X mental retardation protein (FMRP)." (PMID 30402088, 2018). "Fragile X syndrome (FXS) patients are deficient of FMRP due to fmr1 gene silence caused by a CGG trinucleotide amplification on Xq27.3 in the 5′-UTR on chromosome." (PMID 30402088, 2018). "The presence of dynamic mutation in the FMR1 gene localized on the X chromosome (Xq28) is the major cause of Fragile X syndrome." (PMID 29641418, 2018). "Fragile X syndrome (FXS) is caused by the transcriptional silencing of the FMR1 gene (Xq27.3) due to the progressive expansion and subsequent methylation of (CGG) trinucleotide repeats in the 5′-untranslated region of the gene." (PMID 30087288, 2018). "Loss of function mutation in human FMR1 is the major genetic contributor to Fragile X mental retardation syndrome." (PMID 30087606, 2018). "In the fragile X syndrome (which results from the loss of Fmr1 gene function), increased astroglial reactivity has been observed (in mice with genetic deletion of Fmr1 gene)." (PMID 30603062, 2018). "Another mouse model of Fragile X-syndrome, mice that have the I304N mutation in Fmr1, show decreased anxiety behaviour in the OFT and decreased acoustic startle response, as well as hyperactivity and higher exploratory behaviour in the OFT." (PMID 29944857, 2018). "Fragile X syndrome is a genetic condition resulting from FMR1 gene mutation that leads to intellectual disability, autism-like symptoms, and sensory hypersensitivity." (PMID 28451631, 2017). "Absence or dysfunction of Fmr1 gene causes loss of inhibitory functions of its target RNAs and results in excessive protein synthesis, which is one of the main causes of fragile X syndrome." (PMID 28931651, 2017). "For example, the intellectual disability and autism-related gene, FMR1, mutated in Fragile X Syndrome, is necessary for developmental and experience-dependent synaptic pruning as well as pruning in response to MEF2VP16." (PMID 28901289, 2017). "Fragile X mental retardation gene 1 (FMR1) is the gene underlying the disorder Fragile X syndrome (FXS), which results in ID with 15%–30% of patients also displaying ASD phenotypes." (PMID 29209173, 2017). "Fragile X syndrome (FXS) is a neurodevelopmental disorder caused by a trinucleotide (CGG) repeat expansion in the FMR1 gene coding for fragile x mental retardation protein (FMRP)." (PMID 29075560, 2017). "The expanded CGG sequence shows generational instability and women “carriers” of the FMR1 premutation are at risk of passing the mutation to their offspring, which causes fragile X syndrome when the expansion exceeds 200 repeats." (PMID 28835209, 2017).
fragile X syndrome (continued). "Fragile X syndrome (FXS) is an X-linked disorder caused by a CGG repeat expansion in the 5′UTR of FMR1 resulting in gene silencing." (PMID 28919851, 2017). "Cortical hyperexcitability due to abnormal fast-spiking inhibitory interneuron function has been documented in fmr1 KO mice, a mouse model of the fragile X syndrome which is the most common single gene cause of autism and intellectual disability." (PMID 28316753, 2017). "For example, expansion of a CGG repeat in the 5′UTR of the fragile site mental retardation 1 (FMR1) gene causes epigenetic changes that reduce transcription factor binding and are the cause of Fragile X Syndrome." (PMID 29046813, 2017). "Being a sub-category of ASD, fragile X syndrome is identified as a single gene inherited disorder due to mutations or deficiency of FMR1." (PMID 27184741, 2016). "The full mutation form consists of over 200 repeats, which induces hypermethylation of the FMR1 gene promoter and the subsequent silencing of the gene, associated with Fragile X Syndrome (FXS)." (PMID 27983607, 2016). "The FMR1 protein product is widely expressed in neurons, regulates synaptic translation through miRNA interactions, and is disrupted in Fragile X Syndrome, the most common inherited cause of intellectual disability." (PMID 27105825, 2016). "Fragile X syndrome (FXS) is a common cause of intellectual disability that is most often due to a CGG-repeat expansion mutation in the FMR1 gene that triggers epigenetic gene silencing." (PMID 27768763, 2016). "Mutations of the FMR1 gene in humans result in CGG repeat polymorphisms or in the deletion of FMRP protein contributing to Fragile X syndrome, the most common inherited form of intellectual disability." (PMID 27909399, 2016). "Fragile X syndrome (FXS) is an inheritable neuropsychological disease caused by expansion of the CGG trinucleotide repeat affecting the fmr1 gene on X chromosome, resulting in silence of the fmr1 gene and failed expression of FMRP." (PMID 27239350, 2016). "Fragile X syndrome is caused by the loss of FMRP due to the expansion of a CGG repeat in the promoter region of the Fmr1 gene." (PMID 27517961, 2016). "Fragile X Syndrome (FXS) results from a mutation in the Fmr1 gene, encoding the protein Fragile X Mental Retardation Protein (FMRP1)." (PMID 27746717, 2016). "Full mutation alleles (FM: greater than 200 CGG repeats) are associated with silencing of FMR1 through methylation of the promoter region located in the 5′ untranslated region, resulting in a neurodevelopmental disorder known as Fragile X syndrome." (PMID 27959330, 2016). "The second genetic cause of mental retardation in the world, the fragile X syndrome (or Martin-Bell syndrome), is caused by a mutation in the regulatory region of the FMR1 gene on the X chromosome." (PMID 27051666, 2016). "FMRP is the product of the FMR1 gene which is associated with fragile X syndrome, the most common cause of familial intellectual disability that primarily affects males." (PMID 25689425, 2015). "Fragile X syndrome is caused by mutations in the FMR1-gene, which is characterized by an expansion of a CGG triplet in the 5’ UTR." (PMID 26222316, 2015). "For example, mutations in the RNA-binding protein, fragile X mental retardation 1 protein (FMR1), are associated with fragile X syndrome patients." (PMID 26635721, 2015). "Cleavage of APP can produce β-amyloid (Aβ), which is overexpressed in the brain of Fmr1 knockout mice, suggesting a pathogenic role in fragile X syndrome." (PMID 25767435, 2015). "Fragile X syndrome (FXS) is a genetic condition caused by a mutation in the FMR1 gene resulting in cognitive impairment and behavioural problems." (PMID 25063082, 2015). "Its absence (due to silencing of the FMR1 gene) causes fragile X syndrome, an X-linked neurodevelopmental disorder." (PMID 26437437, 2015).
fragile X syndrome (continued). "Fragile X Syndrome, a leading cause of inherited intellectual disability and autism, arises from transcriptional silencing of the FMR1 gene encoding an RNA-binding protein, Fragile X Mental Retardation Protein (FMRP)." (PMID 25849048, 2015). "Our findings strongly support the notion that genetic mechanisms other than CGG repeat expansions and deletions in the FMR1 locus can underlie fragile X syndrome." (PMID 25693964, 2015). "Fmr1 has long been associated with developmental cognitive impairment such as fragile X syndrome (FXS) and, found to be accompanied by epigenetic modification along with genetic anomalies." (PMID 25629700, 2015). "Further expansion of the CGG repeat to greater than 200 in the offspring of FPM carriers leads to the full mutation, silencing of FMR1 expression and fragile X syndrome (FXS), the major known inherited cause of intellectual disability." (PMID 25136376, 2014). "For example, loss of function of Fragile X Mental Retardation 1 gene (FMR1) causes Fragile X syndrome with up to 90% of affected children exhibiting ASD symptoms." (PMID 25170769, 2014). "Expansion of a CGG-repeat element within the human FMR1 gene is responsible for multiple human diseases, including fragile X syndrome and fragile X-associated tremor/ataxia syndrome (FXTAS)." (PMID 24743386, 2014). "Fragile X syndrome results from FMR1 gene silencing, whereas FXTAS is associated with an increase in transcription and toxicity of the CGG-repeat-containing mRNA." (PMID 24743386, 2014). "In a second screening step, characterization of CGG size and/or methylation status of the FMR1 alleles associated with DBS at the low extreme of the FMRP distribution would indicate the presence of the fragile X syndrome." (PMID 25348928, 2014). "The best studied is the FRAXA site in the FMR1 gene, where large expansions cause fragile X syndrome, the most common inherited ID syndrome." (PMID 24763282, 2014). "FMR1_7, where FMR1 is a causative gene of the fragile X syndrome, was revealed to bind specifically to internal and bulge loops." (PMID 24447569, 2014). "Further expansion beyond 200 CGG repeats, or full mutation, leads to FMR1 gene silencing and results in Fragile X syndrome (FXS)." (PMID 24005575, 2014). "An example is the Fragile X mental retardation gene 1 (FMR1), whose silencing causes the Fragile X syndrome, the most common form of ID and autism, also characterized by physical hallmarks." (PMID 24733999, 2014). "The Fragile X syndrome is a monogenetic disorder caused by mutations of the FMR1 gene, located in chromosome X (Xq27.3) and encoding for the Fragile X mental retardation protein (FMRP), which is involved in the translation of a variety of mRNAs." (PMID 25072038, 2014). "FRAXA is a rare, folate sensitive fragile site (FSFS) associated with a trinucleotide repeat (CGG) expansion mutation in the 5′ UTR of the FMR1 gene resulting in fragile X syndrome, the most common inherited intellectual disability syndrome." (PMID 24763282, 2014). "Fragile X syndrome (FraX) is a heritable neurological disorder caused by an abnormal increase of the CGG-triplet number in the promoter region of the gene FMR1 (fragile X mental retardation 1) in humans." (PMID 26740770, 2014). "In Fragile X syndrome patients, the FMR1 allele containing a (CGG)n>200 expansion in the 5′UTR is fully methylated and transcriptionally silenced." (PMID 24787137, 2014). "The first such report concerned Fmr1, the zebrafish homolog of FMR1, a highly-conserved gene that is mutated in human Fragile X Syndrome." (PMID 24945275, 2014). "Human FMR1 is located on chromosome Xq27.3 and inactivation of FMR1 expression leads to the Fragile X syndrome in human, the first cause of inherited mental retardation." (PMID 23555284, 2013). "Single nucleotide mutations in the iduronate 2-sulfatase (IDS) gene at Xq28 most commonly cause Hunter syndrome while a CGG expansion in the FMR1 gene at Xq27.3 is associated with Fragile X syndrome." (PMID 23634718, 2013).
fragile X syndrome (continued). "The Fragile X-Related 1 gene (FXR1) is a paralog of the Fragile X Mental Retardation 1 gene (FMR1), whose absence causes the Fragile X syndrome, the most common form of inherited intellectual disability." (PMID 23555284, 2013). "Fragile X syndrome is caused by the loss of FMRP expression due to methylation of the FMR1 promoter." (PMID 24020679, 2013). "Fragile X syndrome (FXS) is a common form of inherited intellectual disability caused by an expansion of CGG repeats located in the 5′ untranslated region (UTR) of the FMR1 gene, which leads to hypermethylation and silencing of this locus." (PMID 23356558, 2013). "Fragile X Syndrome is an X-linked disorder, the most common inherited form of ID, caused by a trinucleotide repeat in the Fragile X mental retardation 1 (FMR1) gene." (PMID 24198778, 2013). "Fragile X syndrome, one of the most frequent human genetic diseases, is caused by the silencing of the FMR1 gene that codes for a heterogeneous set of Fragile X Mental Retardation protein (FMRP) isoforms." (PMID 24204304, 2013). "Fragile X syndrome is usually associated with the expansion of the CGG trinucleotide repeat in FMR1 at Xq27.3 region, deletion of FMR1 has also been reported in males with Fragile X." (PMID 23634718, 2013). "The fragile X syndrome is caused by the transcriptional silencing of FMRP expression, as a result of hypermethylation on the abnormally high number (>200) of trinucleotide CCG insertions at the fmr1 gene locus." (PMID 23988237, 2013). "We next considered other X-linked mental retardation conditions including Fragile X syndrome as the FMR1 gene is also located in the deletion region and FMR1 deletions are associated with Fragile X syndrome." (PMID 23634718, 2013). "Fragile X syndrome is caused by the loss of the FMR1 gene product, fragile X mental retardation protein (FMRP)." (PMID 22655085, 2012). "Fragile X syndrome is a common inherited form of mental retardation caused by the lack of fragile X mental retardation protein (FMRP) because of Fmr1 gene silencing." (PMID 23119095, 2012). "Fragile X syndrome (FXS) is caused by the expansion of a CGG repeat in the 5′ untranslated region of the FMR1 gene located at Xq27.3." (PMID 22738402, 2012). "Of the small percentage of individuals with genetically correlated ASD, mutations in the X-chromosome linked fragile X mental retardation gene 1 (FMR1) gene in Fragile X syndrome are the most prevalent." (PMID 22022567, 2011). "The mutation of FMR1 triggers abnormal methylation, resulting in a loss of FMR1 expression in the lymphoblastoid cells in Fragile X syndrome, and such loss of FMR1 expression was also reported in the frontal cortex of postmortem brains from subjects with ASD." (PMID 21935445, 2011). "Myotonic dystrophies (DM1 and DM2) are caused by repeat expansions in RNA, while Fragile X syndrome (FXTAS) is caused by a repeat expansion in the 5’UTR of the FMR-1 gene." (PMID 21915392, 2011). "Fragile X syndrome (FXS) is a well known neurodevelopmental disorder caused by loss of fragile X linked mental retardation protein (FMRP) which is encoded by Fmr1 gene." (PMID 21314987, 2011). "Nearly all cases of fragile X syndrome are caused by a mutation in which a DNA segment known as the CGG triplet repeat is expanded within the FMR1 gene." (PMID 22937247, 2011). "Expansion to greater than 200 CGGs leads to transcriptional silencing of FMR1, causing Fragile X Syndrome, a common inherited cause of mental retardation." (PMID 21170301, 2010). "One of the genes known to be associated with POF is FMR1 (Fragile X mental retardation), located at Xq27.3 and responsible for Fragile X Syndrome (FXS)." (PMID 20646274, 2010). "The examination of his mentally retardedgrandson revealed the FMR1 full mutation, thus establishing thediagnosis of fragile X syndrome." (PMID 29213666, 2010).